NCK1 (NCK adaptor protein 1)
Diseases named in the same sentence as NCK1 in open-access papers (continued):
Sharing a sentence is not in itself a finding about the gene and the disease.
phobias (1 paper, 2022). "It would be interesting to further examine whether the level of Nck1 is different in patients that suffer from phobias or that experienced a traumatic event that leads to an increased long-term fear response." (PMID 36371406, 2022).
sarcoma (1 paper, 2011). A usually aggressive malignant neoplasm of the soft tissue or bone. "As expected, we found no change in the protein levels of Nck1 or CrkII, a SH2-SH3 domain-containing adaptor protein previously identify as an oncogene and recently reported to regulate sarcoma cell proliferation." (PMID 21992144, 2011).
schizophrenia (1 paper, 2025). A major psychotic disorder characterized by abnormalities in the perception or expression of reality. "Regarding intelligence and schizophrenia, MAAT identified 21 genes with high association levels in these two traits, where the significant function of ACTR1A, C22orf46, CKB, CYP2D6, LRRC37A, NCK1, and ZMAT2 have been well validated in large-scale GWAS studies." (PMID 39905509, 2025).
Thrombosis (1 paper, 2024). "Furthermore, our results provide new insights into the relationship between platelet NCK1, platelet activation, and arterial thrombosis, and demonstrate the role of phosphorylation of sytanxin‐11 in these processes." (PMID 38922767, 2024). "For evaluating venous thrombosis, we established an inferior vena cava stenosis model and found that thrombus length and weight did not significantly differ between NCK1−/− and WT mice." (PMID 38922767, 2024).
cancer (14 papers, 2011 to 2025). A tumor composed of atypical neoplastic, often pleomorphic cells that invade other tissues. "We propose that NCK1 not only contributes to cancer predisposition but is also involved in cancer progression and prognosis." (PMID 31214250, 2019). "According to pan-cancer datasets, 0.3% of patients had NCK1 somatic mutations, including 102 non-silent mutations from 97 patients, and four fusion variants impaired NCK1 in four patients." (PMID 31214250, 2019). "In general, our results support NCK1 as a candidate cancer gene; however, the underlying mechanisms requirefurther investigation." (PMID 31214250, 2019). "The NCK1 mutations were significantly enriched in the cancer cohort, non-cancer cohort, and general cohort in comparison to the control cohort (Fisher-test; P < 0.001)." (PMID 31214250, 2019). "Second, we inspected the occurrence of somatic mutations in NCK1 among pan-cancer datasets since the somatic event is another important factor involved in cancer progression." (PMID 31214250, 2019). "Therefore, NCK1 might be an invisible participant in tumor progression, because NCK1 mutations rarely occur in cancer patients." (PMID 31214250, 2019). "In conclusion, our results support that NCK1 could be a candidate cancer predisposition gene." (PMID 31214250, 2019). "A previous report has suggested that TKs5 interacts with Rab40b or Nck1 to regulate the initiation and maturation of invadopodia, structures crucial for cancer cell invasion and metastasis." (PMID 40575485, 2025). "Even though it has been demonstrated that p17 modulates suppression of TKs5, NCK1, Rab40b, and MMP9 and reduces complex formation of FAK/Src and TKs5/NCK1 in B16-F10 cancer cells, the impact of p17 on the formation of invadopodia is not yet clear." (PMID 39066315, 2024). "Pirin also interacts with cytoplasmic protein NCK1, which mediates cancer metastasis as well as functions as an intracellular messenger leading to angiogenesis in the ERBB signaling pathway (KEGG entry: hsa04012)." (PMID 38033031, 2023). "If we inhibit expression of NCK1 or GSTP1 in cancer, we can expect their target gene expression to be similar to the control." (PMID 26336805, 2015). "Nck1 and its paralog Nck2 are elevated in many cancers, and their overexpression promotes malignant transformation." (PMID 25137142, 2014). "Expression of Nck1 and Nck2 proteins in various cancer cell lines at different stages of progression were analyzed by western blots." (PMID 21992144, 2011). "However, the expression of IFIT5 and NCK1 were positively correlated with the immune score in most cancers." (PMID 36226166, 2022). "For instance, the variant NCK1 (p.D73H), identified from the pedigree F2887, occurred once in about 7,000 cancer samples, but not in about 60,000 controls according to the genomAD datasets." (PMID 31214250, 2019). "In general, the roles of NCK1 in tumor progression could be genomic context dependent and differentiated in cancer types." (PMID 31214250, 2019). "In addition, our results also suggest that the tumor-promoting role of NCK1 might be a cancer subtype dependent." (PMID 31214250, 2019). "In addition, we imagine that many more cancer genes like NCK1 might exist." (PMID 31214250, 2019).
tumor (12 papers, 2015 to 2024). "In recent years, studies have confirmed that NCK1 is highly expressed in some tumors, and is associated with enhanced tumor proliferation, migration and invasion." (PMID 37366642, 2023). "Three tumours contained mutations in ERBB2/RAS/RAF/MEK pathway members or regulators: an ARAF mutation in combination with a NCK1 mutation, a PAK1 mutation in combination with a NF1 mutation, and an ERBB2 mutation in combination with a TSC1 mutation." (PMID 26506417, 2015). "NCK1 covers aspects of tissue development and homeostasis, invasiveness of tumor cells, and immune cell function." (PMID 34880901, 2021). "On the one hand, overexpression of NCK1 shows oncogenic roles, and the high expression of NCK1, at least in basal-like BC, contributes to tumor proliferation and metastasis." (PMID 31214250, 2019). "To further prove that, we assessed the NCK1 mRNA expression level among 99 tumor-normal matched samples from TCGA-BRCA." (PMID 31214250, 2019). "NCK1 Divergent transcript (NCK1-DT or NCK1-AS1) is a recently identified long non-coding RNA (lncRNA) with the previously documented roles in promoting both tumor growth and resistance to cisplatin (DDP) in cervical cancer." (PMID 39130630, 2024). "However, the expression of NCK1 mRNA in tumor samples was significantly lower than the matched normal samples, which was also observed across different tumor stages." (PMID 31214250, 2019). "These phosphorylation events are essential for cellular invasion and distal tumor metastases formation through multiple mechanisms ultimately creating binding sites for scaffolding platforms composed by proteins such as Arp2/3, cofilin, N-WASp, Grb2, Nck1 and others." (PMID 34088320, 2021). "Given this, we supposed that NCK1 might involve in tumor invasion." (PMID 31214250, 2019). "The non-catalytic region of tyrosine kinase adaptor protein 1 (NCK1) is highly expressed in some tumors, and can promote tumor growth, invasion and migration." (PMID 37366642, 2023). "MMP-2 and Nck1 (non-catalytic region of tyrosine kinase adaptor protein 1) were the most frequently overexpressed invadopodia regulators in GBM compared to non-tumor brain tissue." (PMID 33050088, 2020). "For instance, NCK1 is required for EGFR-mediated cell migration and tumor metastasis." (PMID 31214250, 2019). "Consistent with a tumor-promoting role of PINCH, it has been shown that PINCH interacts at focal adhesions sites with parvins, ILK, Nck1, Rsu-1, and several other partners to promote cell spreading, migration, and apoptosis resistance, features important for tumor cells." (PMID 29755929, 2018).
infection (4 papers, 2007 to 2022). The state of being infected such as from the introduction of a foreign agent such as serum, vaccine, antigenic substance or organism. "Specifically, genetic screens conducted to uncover effectors of Orsay virus infection identified the nck-1 and wsp-1 genes, which encode the worm orthologs of known interactors of mammalian TNK2/ACK1 necessary for infection by multiple forms of picornaviruses." (PMID 35984862, 2022). "Here we demonstrate roles for three human genes, TNK2, WASL, and NCK1, in infection by multiple picornaviruses." (PMID 31769754, 2019). "Our data represent the first demonstration that WASL and NCK1 are important for infection by picornaviruses such as EMCV, CVB3, enterovirus D68, and poliovirus." (PMID 31769754, 2019). "After screening a panel of mammalian viruses, we found that multiple picornaviruses, including EMCV, CVB3, enterovirus D68, and poliovirus, rely on TNK2, WASL, and NCK1 for infection in different cell lines." (PMID 31769754, 2019). "(B) Virus titer for EMCV multiplication on TNK2, WASL, and NCK1 single, double, triple gene knockout and Ctrl cells at 24 hr post infection at an MOI of 0.01." (PMID 31769754, 2019). "In order to elucidate the function of TccP2, we carried out infections of Nck1–/Nck2– fibroblast cell lines with EPEC 1 E2348/69 expressing tccP2_B171 (pICC365)." (PMID 17526832, 2007). "Accordingly, we compared the ability of EPEC 2, EPEC 1 and EHEC O157 : H7 to induce actin-pedestal assembly during infection of Nck1−/Nck2− and Nck1+/Nck2+ fibroblasts." (PMID 17526832, 2007). "Phalloidin staining and quantification of the efficiency of pedestal formation revealed that EDL933 was able to induce actin accretion during infection of an Nck1−/Nck2− fibroblast cell line, at a similar efficiency to infection of a control Nck1+/Nck2+ fibroblast cell line." (PMID 17526832, 2007). "(B) Left - The graph shows quantification of GFP-Nck:RFP-A3 fluorescence intensity ratio on virus particles in live mouse embryonic fibroblasts (MEFs) lacking both Nck1 and Nck2 and stably expressing GFP-Nck1 at 16 hr post-infection." (PMID 35796545, 2022).
retinopathies (2 papers, 2018 to 2021). "Altogether, the data suggest that inhibition of NCK1/2-dependent pericyte migration holds promise as a new strategy to treat retinopathies." (PMID 30150707, 2018). "Loss of Nck1 and Nck2 in mural cells prevents NVT formation and vascular leakage and promotes revascularization, suggesting PDGFRβ-Y1009/NCK signaling as a potential target for the treatment of retinopathies." (PMID 30150707, 2018). "Similarly, Nck1/2 deletion, and to a lesser extent endothelial-specific Nck2 deletion, reduces pathological angiogenesis in the oxygen-induced retinopathy model, whereas Nck1 deletion has no or minimal effect." (PMID 34124074, 2021).
NCK1 also shares sentences with these, for which no sentence is quoted: cervical squamous cell carcinoma (2 papers); coronary artery disease (1); Diabetic Nephropathy (1); Hypertension (1); Miscarriage (1); Obesity (1); ovarian carcinoma (1); stomach adenocarcinoma (1); uterine endometrioid carcinoma (1).